RNU6-460P (RNA, U6 small nuclear 460, pseudogene)
Gene: Small nuclear RNA gene on chromosome 5 (138,116,573 to 138,116,680, forward strand). Ensembl gene ENSG00000212460.
Homologues: Orthologues: chimpanzee U6 (98% identical), macaque U6 (94% identical). Paralogues in human: RNU6-1060P (85% identical), RNU6-949P (85% identical), RNU6-1024P (83% identical), RNU6-12P (83% identical), RNU6-132P (83% identical), RNU6-13P (83% identical), RNU6-15P (83% identical), RNU6-19P (83% identical), RNU6-32P (83% identical), RNU6-41P (83% identical), RNU6-429P (83% identical), RNU6-47P (83% identical), and 1289 more.